TWIST1 (twist family bHLH transcription factor 1)
Diseases named in the same sentence as TWIST1 in open-access papers (continued):
Sharing a sentence is not in itself a finding about the gene and the disease.
tumor (continued). "Twist2, while less well known than Twist1, plays essential roles in strengthening EMT programs and helping tumor cells survive." (PMID 41596524, 2026). "The IHC analysis of xenograft tumor tissues showed that the overall staining intensity of PCNA, Ki67, and TWIST1 was markedly increased in the SOX11 overexpression group but decreased in the SOX11 knockdown group when compared with the control group." (PMID 41511366, 2026). "Meanwhile, high matrix stiffness enhances the nuclear localization of TWIST1 by freeing it from its cytoplasmic binding partner G3BP2, and induces EMT to promote tumor invasion and metastasis." (PMID 40211368, 2025). "As a core transcription factor of EMT, TWIST1 upregulation suppresses E-cadherin expression and induces mesenchymal marker expression, ultimately promoting the EMT process and tumor progression in TC." (PMID 40530008, 2025). "In the subgroup of patient tumour samples with an elevated accumulation of IL‐11, EMT genes (SNAI1, AXL and TWIST1) and hypoxia factor 1 (HIF1A) were over‐expressed compared with the subtype with a lower accumulation of IL‐11." (PMID 40673604, 2025). "Previous studies have demonstrated that Twist1 plays an important role in the EMT and metastasis of tumor cells." (PMID 41082269, 2025). "In a growing tumor, extracellular cues can trigger TWIST1 expression, leading to EMT and the invasion of cancer cells from the primary tumor." (PMID 39851508, 2025). "In this study, we found that FAM64A was upregulated in OC tumor tissues and positively correlated with EMT-related transcription factor TWIST1 expression, indicating that FAM64A has vital significance for the development of OC." (PMID 40424038, 2025). "Knockdown of MELK results in reducing tumor cell invasion and migration, likely by diminishing the levels of matrix metalloproteinase 7 (MMP7), N-catenin, twist family BHLH transcription factor 1 (Twist1), and snail family transcriptional repressor 2 (Snai2)." (PMID 41291696, 2025). "In this case, SC-derived CXCL5 by binding to its receptor CXCR2 in tumour cells activates PI3K/Akt/GSK-3β signalling, increasing the expression of the EMT-TFs Snail1 and Twist1 in these cells and also in hepatocellular carcinoma cells." (PMID 40037534, 2025). "ECHS1 expression was notably reduced in tumor tissues, whereas GCDH, YEATS2, H3K27cr, and Twist1 exhibited increased staining intensity in tumor sections compared to the adjacent normal tissues." (PMID 40810390, 2025). "These included LGR5 as a stem cell and regeneration mRNA marker, SNAIL and TWIST1 as markers of epithelial–mesenchymal transition; and IL-8, CCL2, and COX2 as pro-inflammatory tumor microenvironment markers." (PMID 40476597, 2025). "In addition, IHC staining of mice tumor sections revealed that overexpressing circLRBA could increase the expression of Twist1 and reduce the level of E‐cadherin, whereas circLRBA silencing led to low expression of Twist1 and high expression of E‐cadherin." (PMID 41082269, 2025). "At the same time, the decrease in MMP-2, MMP-9 SNAI1 and TWIST1 protein levels in IL-22 + LY294002 cells indicated that inhibition of the PI3K/AKT signaling pathway reduced MMP expression, attenuating tumor cell invasion and metastasis." (PMID 39073546, 2024). "Pearson analysis also revealed a significant positive correlation relationship between TWIST1 and CD274 mRNA expression levels in individual tumor samples of this dataset (central and right panels)." (PMID 38893094, 2024). "The IHC experiment results showed that the expression of TWIST1 and MMP2 was significantly increased in tumor stage lesion of MF, indicating an increasing level of EMT and CAF-related matrix remodeling." (PMID 39963655, 2024). "Twist1 is also known to transcript CCL2 and CXCL12 that can recruit pro-tumor myeloid cells, serving as a potentially additional mechanism to induce vascular niche-mediated Mφ immunosuppression." (PMID 38416830, 2024).
tumor (continued). "Twist family members comprise Twist‐1 and Twist‐2, both of which are found to be upregulated and induce EMT process in tumor tissues." (PMID 39092293, 2024). "Twist family bHLH transcription factor 1 (TWIST1), a basic helix-loop-helix (BHLH) transcription factor, plays a pivotal role in activating the EMT and promoting tumor invasion." (PMID 38544822, 2024). "We reveal a spatially restricted, Twist1/SATB1-mediated sequential transcriptional activation mechanism, through which tumor ECs produce osteopontin to promote immunosuppressive macrophage (Mφ) phenotypes." (PMID 38416830, 2024). "For example, in a mouse model of squamous cell carcinoma (SCC), researchers discovered that TWIST1 can induce EMT and enable tumor cells to spread into the bloodstream." (PMID 39598229, 2024). "Conversely, Snail, Slug, and Twist1, as upstream regulators of EMT markers, were significantly reduced in melittin-treated tumor cells compared to untreated cells." (PMID 39519238, 2024). "Further analysis of the HCT116 tumour tissue lysates showed that BEST4 deterred EMT by upregulating E-cadherin, and downregulating VIM and TWIST1." (PMID 39699952, 2024). "PLA results on tumor tissue illustrated that the supplementation of VD3 promotes the interaction between YY1 and VDR at the tumor site, with a significant increase also observed in the interaction between VDBP and Twist1." (PMID 38164156, 2024). "These cell-intrinsic signaling pathways cooperate to induce the transcriptional activation of EMT-TFs, such as SNAIL, ZEB1/2, and Twist1/2, subsequently triggering the EMT process for induction of the transition to the mesenchymal state of the tumor cells." (PMID 38792011, 2024). "SQSTM1-mediated stable expression of TWIST1 promotes EMT in vitro and promotes tumor growth and metastasis in mice." (PMID 37403096, 2023). "Tumor cells re-express EMT genes, such as TWIST1, to jumpstart metastasis in response to a variety of signals." (PMID 38139368, 2023). "Taken together, our investigation revealed that USP51 promotes the stabilization of the TWIST1 protein by deubiquitinating TWIST1, which enhances the stemness of NSCLC cells, leading to NSCLC tumor proliferation." (PMID 37422632, 2023). "TWIST1 enhances glucose uptake by upregulating GLUT1, thereby reprogramming glucose metabolism in tumor cells." (PMID 36936141, 2023). "Dramatically decreases in the tumor weight and volume were observed upon USP51 depletion, and increasing TWIST1 expression reversed the effect of USP51 knockdown on decreasing the tumor weight and volume." (PMID 37422632, 2023). "In recent years, the roles of TWIST1 and other EMT factors in cancer have expanded greatly as our understanding of tumor progression has advanced." (PMID 38139368, 2023). "EGFR modulates PCa tumor growth, invasion, and bone metastasis and seems to regulate several oncogenic genes, such as twist family BHLH transcription factor 1 (TWIST1)." (PMID 37627055, 2023). "The EMT tumor population showed increased binding accessibility for known positive regulators of EMT, such as TWIST1 and JUN." (PMID 36973268, 2023). "Of note, except for HOXA3, TWIST1, and ID1, the other seven genes are all proangiogenic genes that can be expressed and secreted by tumor cells, which implied the potential role of ELK4 in tumor angiogenesis in a paracrine manner in CRC." (PMID 37786278, 2023). "The TWIST1-JAGGED1-NOTCH-KLF4 axis induces stem cell-like features and metastasis, where KLF4 and BMI1 contribute to TWIST1-induced tumor-initiating capacity, and knockdown of BMI1 expression leads to a reduction in the size and number of tumor spheroids." (PMID 37598158, 2023).
tumor (continued). "In response to hypoxia, hypoxia-inducible factor 1α (HIF1α) can up-regulate Twist1 expression to induce EMT and tumor cell dissemination." (PMID 38134227, 2023). "EMT genes like KRT19, CTNNB1 and TWIST1 and the hypoxia marker HIF1A were significantly changed in tumors, indicating altered tumor microenvironment." (PMID 37170215, 2023). "Twist Family BHLH Transcription Factor 1 (TWIST1) is a critical apoptosis inhibitor in embryonic development, tumor metastasis, and initiation." (PMID 37744377, 2023). "For instance, the pro-inflammatory cytokine IL-6 stimulated the expression of Twist1 in normal fibroblasts, leading to their transdifferentiation into CAFs through STAT3 phosphorylation, thereby facilitating tumour invasion." (PMID 38173726, 2023). "TWIST1 is a basic helix-loop-helix (bHLH) transcription factor and is also one of the most important EMT genes involved in embryonic development, tumor progression, and metastasis." (PMID 35052775, 2022). "Thus, although our results suggest that cellular senescence induces TWIST1 expression, there may be a feedback mechanism; TWIST1 may control cellular senescence as reported in mesenchymal stem cells and tumor cells and contribute to PH phenotype through mitochondrial signaling." (PMID 36203755, 2022). "Smurf2 overexpression inhibited the expression of snail, slug, and Twist1/2, which indicated that Smurf2 affected EMT of HCC and inhibited tumor progression by affecting EMT inducible transcription factors." (PMID 35509688, 2022). "Here we confirm the cooperation between TWIST1 and MYCN in defining a transcriptional program in NB supporting in vitro cell proliferation and in vivo tumor growth." (PMID 35022561, 2022). "The Mes tumor subtype predominantly expresses fibroblastic/mesenchymal genes, such as PDGFRA, VCAM1, ZEB1, TWIST1; and extracellular matrix genes, including collagen and FN1 (bolded genes are overlapping with our negative prognostic signature)." (PMID 36555638, 2022). "To conclude, RBM24, as a novel tumor inhibitor gene, inhibits the LN metastasis and EMT by the downregulation of the Twist1 in HSCC." (PMID 36213838, 2022). "High matrix stiffness leads to the release of Twist1 from GAP SH3 domain-binding protein 2 (G3BP2), thereby promoting Twist1 nuclear translocation and enhancing EMT in tumor cells." (PMID 35331296, 2022). "Here, we investigated the synergistic effect of combination treatment with both of these drugs in inducing FoxO1 and repressing Twist1 expression and thereby inhibiting EMT and tumor regression." (PMID 33772986, 2022). "The expression levels of MYC, NR5A2, SNAI1, TWIST1, and STK11 were significantly higher in tumor-adjacent tissues than in the matched EC samples, and this difference was not influenced by the content of cancer cells in cancer-adjacent tissues." (PMID 36140779, 2022). "MAOA promoted PCa metastasis by regulating downstream ROS and Twist1 pathways that mediated Shh/Gli signaling to activate YAP1 transcription in concert with AR to induce epithelial–mesenchymal transition and tumor–stromal cell interactions." (PMID 36452480, 2022). "Previous researches have displayed that TWIST1 is a significant transcription factor that exerts a critical effect in EMT and tumour metastasis." (PMID 35802537, 2022). "Overexpression of other EMT-TFs such as ZEB2, TWIST1, and SNAI1 similarly reduced tumor growth and metastatic load arguing that different EMP states induced by distinct means in MCF-7 cells neither favor tumor progression nor metastasis." (PMID 36008376, 2022). "Additionally, we identify a TWIST1-mediated transcriptional program associated with dismal outcome in NB and involved in the control of pathways mainly linked to the signaling, migration, adhesion, the organization of the ECM, and the tumor cells versus tumor stroma crosstalk." (PMID 35022561, 2022).
tumor (continued). "Upregulation of EMT transcription factors, such as TWIST1, ZEB1/2 and SNAI1/2 have been reported to promote migration and invasion of tumor cells in many types of tumors." (PMID 35205125, 2022). "In PCa, upregulation of TWIST1 through Sox5 increased the migration capacity and mesenchymal phenotype of cancer cells, initiated the EMT program, and promoted tumor lymph node metastasis." (PMID 36127329, 2022). "The expression of TWIST1, CRIPTO1, SOX2, and MSI1 were evaluated in ESCC patients, indicating their role in tumorigenesis and tumor cell aggressiveness." (PMID 36553636, 2022). "RAs within the tumor drive upregulation of survival genes in tumor cells, in particular, GSTA5, BCL2L1, and TWIST1." (PMID 34859239, 2021). "The reduction of Twist1 expression by thymoquinone and tamoxifen significantly inhibits TNBC tumor growth and metastasis and reverses drug resistance in an in vitro tumor cell model and in mice." (PMID 34922602, 2021). "Further study by the same group revealed that GLI1 regulates the expression of EMT-inducing transcription factors, TWIST1 and SNAI1, to promote tumor-initiating cell-like properties and consequently chemoresistance in the resistant sublines." (PMID 34638233, 2021). "Evidence from the tumor stroma points to epigenetic changes favoring the budding process, for example, methylation of TWIST1 and TWIST2 in stromal cells, or changes in miRNA has been found to occur in non-tumor budding regions." (PMID 33843013, 2021). "The findings in our cohort also show that Twist1 and Snai2 can be activated independently in both UC and UCOGC, given that in some cases only, one of these markers is expressed in tumor cells." (PMID 32661742, 2021). "In this regard, TWIST1 expression was investigated in the subcellular locations (cytoplasm and nucleus), while CD105 was mapped in endothelial cells and cytoplasmic tumor cells of CRC tissues." (PMID 33752711, 2021). "Evidently, TWIST1 and SNAI1 levels were markedly elevated in these multidrug-resistant sublines exhibiting heightened tumor-initiating potential." (PMID 34638233, 2021). "Lower levels of expressions of TWIST1 and CD105 were observed in adjacent normal tissues compared to the tumor samples." (PMID 33752711, 2021). "Concordantly, both the TWIST1 and STAT1 are highly and specifically enriched in the F_3 subset which we have annotated as pro-tumor myofibroblasts." (PMID 34921160, 2021). "Thus, the connecting pathway involving Twist1 expression should be further explored, understanding that Twist1 and other associated downstream regulators could be exploitable in therapeutic designs for EMT→MET reversion, particularly at an early stage of tumour development." (PMID 34868979, 2021). "Compared with the primary tumor, in the metastasis group, the mesenchymal markers (CDH2, VIM, TWIST1, SNAI1, ZEB1) and ferroptosis drivers increased, and the epithelial marker CDH1 and ferroptosis suppressor decreased." (PMID 35127731, 2021). "Galván and colleagues first showed that TWIST1 and TWIST2 protein expression are found nearly exclusively in the tumor stroma." (PMID 34768901, 2021). "TWIST1 was expressed at different sites (both nucleus and cytoplasm) in the tumor cells, while CD105 was detected in endothelial cells and cytoplasm of tumor cells of the obtained CRC samples." (PMID 33752711, 2021). "Twist1 overexpression enhances tubular formation and MMP expression in GBM cells, indicating that Twist1 can promote the formation of VM in tumor tissue." (PMID 34213079, 2021). "A previous study identified a relationship between the expression of mesenchymal genes in tumor cells (e.g., SNAI1, TWIST1, and ZEB1) and the extent of clearance." (PMID 34396026, 2021). "It is well known that SNAI1, SNAI2, ZEB1, ZEB2, TWIST1 and TWIST2 are key transcription factors involved in EMT in various types of cancers, and they contribute to enhanced tumour cell migration, invasion and metastasis capacities." (PMID 32488136, 2020).
tumor (continued). "Twist1, a basic helix-loop-helix (bHLH) transcription factor, plays a critical role in promoting EMT, tumor metastasis, cancer stemness and drug resistance." (PMID 32549341, 2020). "The present study shows that the oncogenic transcription factor ISX is a key regulator of EMT and tumor metastasis by modulating the expression of EMT regulators, such as TWIST1 and Snail1." (PMID 31908141, 2020). "Taken together, our results indicate that constitutive Twist1 overexpression partially restores the tumor-promoting capacity of CAFs under DHR treatment, suggesting that the effects of DHR are partially dependent on Twist1 expression." (PMID 32341496, 2020). "Twist1 is an important transcription factor that mediates epithelial-mesenchymal transition (EMT) progression and tumor metastasis." (PMID 31941509, 2020). "In this study, we first identified DHR as an anti-CAF drug candidate using reporter cells expressing Twist1 promoter-GFP and confirmed that DHR repressed tumor progression both in vitro and in vivo by deactivating CAFs." (PMID 32341496, 2020). "Our results suggest that increased RCC2 expression stimulates tumor growth by upregulating IGF1, TWIST1, and IL-6 expression." (PMID 32565805, 2020). "Noteworthy, numerous neoplastic cells were scattered throughout the tumor area and expressed the EMT-related transcription factors TWIST-1, ZEB-1, and HIF-1α." (PMID 33297475, 2020). "The basic Helix-Loop-Helix (bHLH) transcription factor TWIST1 is one of the six transcription factors that control EMT during normal development, but that can also promote EMT and tumor metastasis in cancer cells." (PMID 33227047, 2020). "Twist1 activates other EMT-inducing transcription factors to suppress E-cadherin and promote EMT and tumour metastasis." (PMID 33225905, 2020). "We found that the mRNA expression levels of FABP5, FASN, HSL, TWIST1, VEGF-C, and MMP9 were significantly higher in tumours of the bevacizumab group than those of the control group." (PMID 32550890, 2020). "EMT transcriptional factors, Snail/Slug, Twist1 and ZEB1, are pivotal in regulation of tumor metastasis and stemness." (PMID 32549341, 2020). "miR-15a/16 exerts tumor suppressive roles by targeting multiple oncogenes, including BCL2, TWIST1, MCL1, CCND1 and WNT3A." (PMID 32678069, 2020). "Hypoxia also promotes tumor metastasis by translational regulation of various proteins important in various phases of this process including EMT such as SNAIL1, SNAIL2, TWIST1, TWIST2, TGF-β, Wnt, and Notch." (PMID 32973493, 2020). "The aim of this study was to analyze the expression of SNAIL, SLUG, TWIST1, TWIST2, ZEB1, and ZEB 2 in primary tumor and the correlation with morphological and clinical characteristics of EC." (PMID 33457409, 2020). "In the next step, expression level of stemness relatedgenes (OCT4, SOX2, KLF4, c-MYC and NANOG) and EMTtranscription factors (CDH1, CDH2, SNAIL1, TWIST1,TWIST2 and ZEB1) were evaluated in all tumor samples andmammospheres." (PMID 31376329, 2020). "(d) Serial cross sectional imaging of MYC- (n = 10) and MYC/Twist1-HCC (n = 10) using MRI scan for the abdomen and CT scan for the lungs demonstrate step-wise tumor progression." (PMID 31933479, 2020). "Twist1 overexpression can also increase the synthesis of VEGF, promote vascular expansion and permeability, and accelerate tumor progression." (PMID 33330033, 2020). "Both TWIST1 and ADAM22 were upregulated for patients with higher tumor-stages in two independent cohorts, including GSE45547 and GSE120572." (PMID 32629858, 2020). "Two of the clusters have high expression of genes related to mesenchymal phenotype (e.g., CDH2, SNAI2, ZEB1, TWIST1, and VIM) which were assigned as tumor cells with EMT characteristics (EMT+)." (PMID 32988401, 2020). "Noteworthy, the staining pattern of TWIST1 and NAT1 have appeared to be related to the EMT status of the primary tumor." (PMID 30610490, 2019).